PHEX (phosphate regulating endopeptidase X-linked)
Diseases named in the same sentence as PHEX in open-access papers (continued):
Sharing a sentence is not in itself a finding about the gene and the disease.
osteomalacia (15 papers, 2014 to 2026). Disorder caused by an interruption of the mineralization of organic bone matrix leading to bone softening, bone pain, and weakness. "It has been shown that deleterious PHEX mutations can cause bone deformities, osteomalacia and fractures." (PMID 40287517, 2025). "It is interesting to note in this context that transgenic overexpression of PHEX under different promoters only partially rescued the osteomalacia in Hyp mice (PHEX-tg/Hyp)." (PMID 27035636, 2016). "However, serial analysis of gene expression identified DMP1 and PHEX as overexpressed genes in tumors responsible for tumor-induced osteomalacia and secreting FGF23." (PMID 36776964, 2023). "A recent study identified autoantibodies against PHEX, the gene responsible for XLH, in 5 of 13 patients with acquired FGF23-related osteomalacia without detectable PMTs, thereby defining a novel disease entity termed autoimmune osteomalacia (AIO)." (PMID 41691126, 2026).
X-linked dominant hypophosphatemic rickets (8 papers, 2009 to 2025). "Evaluation of this substance and of the phosphate-regulating gene with homologies to endopeptidase on the X chromosome (PHEX), whose loss of function causes adhr and whose mutation causes xlhr, may provide diagnostic clues 4,5,20." (PMID 19862367, 2009).
autosomal recessive hypophosphatemic rickets (7 papers, 2012 to 2025). Autosomal recessive hypophosphatemic rickets (ARHR) is a hereditary renal phosphate-wasting disorder characterized by hypophosphatemia, rickets and/or osteomalacia and slow growth. "Mutations in either PHEX (XLH, X-linked hypophosphatemic rickets) and DMP1 (ARHR, autosomal recessive hypophosphatemic rickets) cause renal phosphate wasting and its clinical sequelae by primary elevations of FGF23." (PMID 35629904, 2022). "This condition includes several forms: autosomal dominant hypophosphatemic rickets (ADHR) caused by FGF23 mutations, autosomal recessive hypophosphatemic rickets (ARHR) caused by DMP1 mutations, and X‐linked hypophosphatemic rickets (XLH) caused by PHEX mutations." (PMID 40661139, 2025).
enthesopathy (4 papers, 2019 to 2025). "Deletion of Phex in C–/– and C–/–/F–/– mice (C–/–/Hyp and C–/–/F–/–/Hyp) did not lead to further increased immunoreactivity for BMP and IHH target genes or ALP activity in entheses, suggesting PHEX-specific functions are unlikely to play a dominant role in XLH enthesopathy development." (PMID 37490334, 2023).
osteoporosis (4 papers, 2023 to 2025). A condition of reduced bone mass, with decreased cortical thickness and a decrease in the number and size of the trabeculae of cancellous bone (but normal chemical composition), resulting in increased fracture incidence. "Single nucleotide polymorphisms in genes critical for bone homeostasis, including ALPL, DKK1, PHEX, and COL1A1, are associated with osteoporosis and related skeletal pathologies in humans." (PMID 40961770, 2025). "Additionally, we found that expression of Phosphate Regulating Endopeptidase X-Linked (PHEX), an important regulator of bone mineralization, was lower in COPD patients with osteoporosis." (PMID 40287517, 2025).
hyperparathyroidism (3 papers, 2011 to 2025). Hyperfunction of the parathyroid glands resulting in the overproduction of parathyroid hormone. "PHEX mutation was confirmed in 17 (53.1%) patients with non-hyperparathyroidism, 17 (51.5%) patients with secondary hyperparathyroidism, and 2 (50.0%) patients with tertiary hyperparathyroidism." (PMID 40074938, 2025).
nephrocalcinosis (3 papers, 2011 to 2021). Nephrocalcinosis is a disorder that occurs when too much calcium is deposited in the kidneys. "Although the sample size was small and the presence of nephrocalcinosis could be the result of different treatment regimen, our data suggested that the PHEX mutation type might be useful to detect patients at increased risk of developing nephrocalcinosis." (PMID 21902834, 2011).
fibrous dysplasia (2 papers, 2021 to 2026). A genetic, non-inheritable disorder caused by osteoblastic differentiation defects that result in the replacement of bone marrow and trabecular bone by fibrous stroma and immature bone. "The forms of HR caused by the excess of FGF23 are the X-linked form (XLH) caused by an inactivating mutation in the PHEX gene, tumor-induced osteomalacia (TIO), epidermal nevus syndromes, and fibrous dysplasia in McCune–Albright syndrome." (PMID 34208131, 2021).
hereditary hypophosphatemic rickets (2 papers, 2023 to 2025). Hypophosphatemic rickets is a group of genetic diseases characterized by hypophosphatemia, rickets, and normal serum levels of calcium. "Hereditary hypophosphatemic rickets is most commonly the X-linked dominant form due to variants in the PHEX gene located at chromosome Xp22.1-p22.2, but other inheritance patterns exist." (PMID 40533633, 2025).
Hypoinsulinemia (2 papers, 2014 to 2025). A decreased concentration of insulin in the blood. "Moreover, HYP-mice with a PHEX (phosphate regulating gene with homologies to endopeptidases located on the X chromosome) mutation that leads to FGF23 overexpression also display hyperglycemia and hypoinsulinemia." (PMID 40237064, 2025).
secondary hyperparathyroidism (2 papers, 2025). Overproduction of parathyroid hormone in response to influence external to the parathyroid glands. "Rather, it is a consequence of either hypocalcaemia and secondary hyperparathyroidism, increased renal Pi wasting as a result of mutations in the PHEX gene (phosphate-regulating gene with homologies to endopeptidase on the X chromosome) or reduced absorption due to impaired vitamin D actions." (PMID 40791815, 2025).
and copper metabolism disorders (1 paper, 2024). "Associations have also been noted with genetically determined iron and copper metabolism disorders (haemochromatosis, Wilson’s disease), as well as phosphate disorders (X-linked dominant hypophosphataemic rickets due to mutations in the PHEX gene)." (PMID 39088093, 2024).
colon cancer (1 paper, 2008). "In proteolysis, we identified the subtilisin PCSK2, with 4-6 fold increases in 8 of its core probe-sets in MG-thymoma and increases in colon cancer, and the endopeptidases PHEX and ADAMTS20 (proteolysis), both up-regulated in MG-thymoma but not in colon cancer." (PMID 18545673, 2008).
craniosynostosis (1 paper, 2023). Craniosynostosis is defined as the premature fusion of one or more cranial sutures leading to secondary distortion of skull shape resulting in skull deformities with a variable presentation. "The independent impact of PHEX mutation on craniosynostosis will be best answered in animal studies." (PMID 37197318, 2023).
hearing loss (1 paper, 2019). "These confounding effects of specific mutation and genetic background on XLH-related hearing loss would be further compounded when studying genetically diverse patients with XLH that have various PHEX mutations." (PMID 30808384, 2019). "Potential contributions of PHEX and FGF23 to hearing loss were confounded because both mutations extended beyond the Phex coding region, and Gy mutations affected the nearby SmS gene, which has been associated with hearing loss." (PMID 30808384, 2019).
McCune-Albright syndrome (1 paper, 2020). McCune-Albright syndrome (MAS) is classically defined by the clinical triad of fibrous dysplasia of bone (FD), cafe-au-lait skin spots, and precocious puberty (PP). "At diagnosis, one patient was diagnosed as McCune Albright syndrome, two patients with PHEX mutation, and two asymptomatic patients were screened because of affected siblings have normal TPR." (PMID 31514490, 2020).
osteosarcoma (1 paper, 2023). A usually aggressive malignant bone-forming mesenchymal neoplasm, predominantly affecting adolescents and young adults. "Expression of osteocyte markers (i.e., DMP1, MEPE, or PHEX) has been observed in the osteoblastic subtype of human osteosarcoma, indicating that osteocytes may potentially serve as progenitors for osteosarcoma cells." (PMID 37174109, 2023).
periodontal disease (1 paper, 2023). "PHEX (phosphate-regulating endopeptidase homolog, X-linked) deficiency in Hyp-mice has been shown to lead to an altered periodontal phenotype with hypoplasia of the cementum, which could indicate a higher susceptibility to periodontal disease in adult XLH patients." (PMID 38137614, 2023).
genetic disorder (11 papers, 2012 to 2025). "X-linked hypophosphatemia (XLH) is a genetic disorder caused by mutations that inactivate the X-linked phosphate-regulating endopeptidase homolog (PHEX) gene." (PMID 38542517, 2024). "X-linked hypophosphatemic (XLH) rickets is a genetic disease caused due to the inactivation of the PHEX gene (phosphate regulating gene with homology to endopeptidase on the X chromosome)." (PMID 33178527, 2020). "X-linked hypophosphatemic (XLH) rickets is a rare genetic disorder caused by inactivating mutations in the PHEX (phosphate-regulating endopeptidase homolog, X-linked) gene, inherited in an X-linked dominant manner, with an estimated incidence of 3.9 per 100,000 live births." (PMID 40980824, 2025).
bone disorder (3 papers, 2020 to 2023). "Eight AFF patients (NS2‐9) without a clinical suspicion of a monogenic bone disorder carried one or more heterozygous VUS with a CADD score ≥ 20 in P4HB, PHEX, TNFRSF11A, CREB3L1, TCIRG1, SERPINH1, LEPRE1, and PLOD2." (PMID 37076969, 2023).
kidney disease (2 papers, 2024 to 2025). "In addition, while some identified variants (e.g., P779; POLG, P577; PHEX) are not classified as primary kidney disease genes, their detection had significant clinical implications, including avoiding nephrotoxic medications, guiding peri-transplant care, and informing family genetic counseling." (PMID 40282368, 2025).
PHEX also shares sentences with these, for which no sentence is quoted: autosomal dominant hypophosphatemic rickets (6 papers); osteoarthritis (3); tumor (3); dental abscesses (2); Hepatic fibrosis (2); infection (2); allergic reactions (1); amelogenesis imperfecta (1); anemia (1); bacterial infection (1); bone-mineral disorders (1); calcification (1); cancer (1); diabetes (1); epidermal nevus syndrome (1); Fanconi syndrome (1); Gitelman syndrome (1); haemochromatosis (1); Hypercholesterolemia (1); Hyperglycemia (1); hypocalcaemia (1); hypophosphatasia (1); ischemia (1); melanoma (1); metabolic bone disorder (1); nephrolithiasis (1); Nephropathy (1); Neurological disorders (1); Obesity (1); osteogenesis imperfecta (1).
A further 11 diseases each share a sentence with PHEX in 1 paper.